IFNG (interferon gamma)
Diseases named in the same sentence as IFNG in open-access papers (continued):
Sharing a sentence is not in itself a finding about the gene and the disease.
aplastic anemia (24 papers, 2013 to 2026). Anemia resulting from bone marrow failure (aplastic or hypoplastic bone marrow). "For instance, polymorphisms in the IFNγ gene have been linked with high production of IFN-γ, and occur more frequently in patients with aplastic anemia." (PMID 29181334, 2017). "Aberrant p38MAPK activity has been demonstrated in bone marrow-derived myeloid progenitors from patients with MDS or aplastic anemia, which has been explained by increased activity of the myelosuppressive cytokines IFNγ and TNFα, which stimulate p38MAPK activity." (PMID 24614182, 2014). "Interestingly, IFNγ and TNF-α have been described as possibly implicated in the pathophysiology of aplastic anemia and abnormal STAT1 activation was demonstrated in BM samples of few aplastic anemia patients." (PMID 35898506, 2022). "A clinical trial proved that the defective Sirt1 may be correlated to the abnormal IFNγ expression in severe aplastic anemia patients, and activation of Sirt1 signaling by SRT3025 may help improve the inflammatory status of severe aplastic anemia." (PMID 36843938, 2023). "Using experimental models for aplastic anemia, T cells were proposed as key mediators of hematopoietic dysfunction and ultimately BM failure, and in experimental ehrlichiosis, infection-induced expansion of LSK cells was shown to be dependent upon IFNγ production by CD4+ T cells." (PMID 28671989, 2017).
cutaneous melanoma (24 papers, 2012 to 2025). A primary melanoma arising from atypical melanocytes in the skin. "Several tumor-intrinsic factors leading to immune escape and resistance to immune-checkpoint inhibitors have been characterized in cutaneous melanoma, including low tumor antigenicity, disruption of interferon-gamma (IFN-γ) signature, and loss of major histocompatibility complex (MHC) expression." (PMID 35008570, 2021). "We established an effective five‐IFNγ response‐related gene‐based risk score, which has potential to be a novel prognostic signature and may provide insight into tumor immune microenvironment of cutaneous melanoma." (PMID 32902917, 2020). "MBM exhibited lower interferon-gamma (IFNγ) scores and T cell-inflamed scores compared to primary cutaneous melanoma (PCM) or extracranial metastases (ECM), which was independent of tumor mutational burden." (PMID 37964004, 2023). "Overall, our findings suggest that TMBhigh skin melanomas correlate with high levels of IFNγ, CD8+ T-cells in the TME, cancer neoepitopes, as well as high expression of PD-L1 and further immune receptors." (PMID 36389735, 2022). "We also noted that cell surface expression of HLA-DR, NGFR, and PD-L2 was significantly lower in UVM compared to cutaneous melanoma, both at baseline and post-IFNγ stimulation." (PMID 29977240, 2018). "Here, we evaluated somatic mutations in IFNG and other IFN-γ-related genes in skin melanoma, and questioned whether their presence associates with gene expression." (PMID 36389735, 2022). "In UVM lines, however, the protein expression of HLA-DR, NGFR, PD-L1, and PD-L2 post-IFNγ stimulation was significantly lower than observed in cutaneous melanomas, and this was consistent with low baseline expression of HLA-DR, NGFR, and PD-L2 in the UVM cells." (PMID 29977240, 2018). "Blocking ERK activation rescued IFNγ-mediated apoptosis in 17 of 23 (~ 74%) cell lines representing BRAF, NRAS, NF1 mutant, and triple wild type subtypes of cutaneous melanoma." (PMID 37803324, 2023). "The transcript expression of STAT1, STAT3, and IRF1, three key transcription factors of the IFNγ signaling cascade, were also lower in the TCGA UVM dataset compared to the TCGA cutaneous melanomas." (PMID 29977240, 2018). "Five of eight UVM cell lines responded to IFNγ treatment with a decreased proportion of S phase cells and this was not a common response in our panel of cutaneous melanoma cells." (PMID 29977240, 2018).
thyroiditis (24 papers, 2011 to 2026). Inflammation of the thyroid gland. "In addition, thyroid follicular cells of AITD patients abnormally express interferon-gamma (IFNG)-induced MHC class II molecules which enable the presentation of thyroid autoantigens, facilitating T cells activation." (PMID 34981746, 2022).
tularemia (24 papers, 2010 to 2025). Tularemia is an infection caused by the bacterium Francisella tularensis. "Previous reports have underlined the role of cell-mediated immunity and IFNγ in the host response to Francisella tularensis infection." (PMID 20585449, 2010). "We believe this result likely underscores the importance of the production of IL-12 and IFNγ and of a potent inflammatory response in the protection from tularemia." (PMID 41406154, 2025). "Following Francisella tularensis infection, DCs accounted for 15-50% of innate IFNγ producing cells." (PMID 34956227, 2021). "Administration of IFNγ increased the survival of Il-18-/- mice, suggesting that the lower resistance to tularemia is due to an inability to produce IFNγ." (PMID 25768794, 2015). "IL-18-deficient mice quickly succumbed to infection with high organ bacterial burdens and low levels of IFNγ, a cytokine that has been shown to be critical for protection from tularemia." (PMID 25768794, 2015). "Administration of IFNγ rescued the survival of Il-18-/- mice, suggesting that their decreased resistance to tularemia is due to inability to produce IFNγ." (PMID 25768794, 2015). "Similarly, IL-17A is required for the generation of protective IFNγ responses during pulmonary tularemia." (PMID 39772023, 2024). "Serum levels of eotaxin, G-CSF, IFNα, IFNγ, IL-1β, IL-2, IL-6, IL-8, IL-10, IP-10, MCP-1, MIP-1α, MIP-1β, and PDGF were significantly increased in tularemia patients when compared to healthy controls and/or between different time points of sampling." (PMID 33114188, 2020). "In the initial phase, interferon gamma (IFN-γ) and TNF-α are necessary for the resolution of tularemia." (PMID 22783145, 2012). "Given the requirement for the mature neutrophils early in infection and the late appearance of elevated IFNγ, it is unlikely that resistance to Ft in the absence of Nlrp3 results from transcriptional alterations in lung Th1/Th2 cytokines during pulmonary tularemia." (PMID 27926940, 2016).
Cerebral ischemia (23 papers, 2011 to 2025). Restriction of arterial blood supply to the brain associated with insufficient oxygenation to support the metabolic requirements of the tissue. "CXCL9, a chemoattractant for T lymphocytes and NK cells triggered by interferon-gamma, is still not clearly understood in the context of cerebral ischemia." (PMID 38861234, 2025). "Moreover, sympathetic activity can influence the function of invariant natural killer T cells in liver, leading to systemic immune suppression via elevated interferon-gamma (IFN-γ) after experimental cerebral ischemia." (PMID 34572077, 2021). "However, in one study, IDO expression remained unchanged in an animal model of cerebral ischemia in IFNγ−/− mice compared with the wild types." (PMID 31153376, 2019). "Utilizing the BV2 microglial cell line, they reported induction of Abcc8/Sur1 and Kcnj11/Kir6.2 following exposure to LPS + IFNγ for 48 h, as well as enhanced immunolabeling of microglia in vivo for subunits of Sur1-Kir6.2 (KATP) in cerebral ischemia." (PMID 27246103, 2016). "Stem cell-derived exosomes (SC-Exos) attenuated neuronal apoptosis, augmented interferon-gamma (IFN-γ) and Bcl-2, and decreased IL-1α, IL-2, TNF-α, Bax, cytochrome C (CytC), and cleaved caspase-3 and caspase-9 production in rats with cerebral ischemia/reperfusion (I/R) injury." (PMID 36986865, 2023). "However, in response to brain ischemia, downregulation of Notch and BMP activity, and concomitant involvement of interferon gamma signaling, induce the activation/priming of NS/PCs." (PMID 33716653, 2021).
Hepatic steatosis (23 papers, 2013 to 2026). Steatosis is a term used to denote lipid accumulation within hepatocytes. "Both elafin delivery approaches also significantly increased circulating leptin levels and significantly reduced circulating IFNγ levels, food consumption, fat mass gain, fasting blood glucose levels, and liver steatosis of the HFD-treated male mice." (PMID 32733043, 2020). "Elafin overexpression inhibited liver steatosis in the HFD-treated male mice 5,38, which was reversed by injection of IL-1β or IFNγ protein." (PMID 32733043, 2020). "Another study showed that synergistic treatment of Bilophila wadsworthia promoted high-fat diet (HFD)-induced local and systemic inflammation (upregulation of interferon-gamma or IFN-γ and IL-6), intestinal barrier interruption, BA and glucose metabolism dysregulation, and hepatic steatosis." (PMID 38283696, 2024). "Finally, Kamut could significantly improve the liver steatosis grade by reducing circulating proinflammatory TNF-α, IL-8, interferon-gamma (IFNγ), and the interleukin-1 receptor antagonist (IL-1RA)." (PMID 34426744, 2021). "As the inflammation in the hepatocytes is a critical transformation from simple liver steatosis to steatohepatitis, FAT10 and related TNFα/IFNγ changes via NFκB and/or STAT3 pathways could be the candidate molecular parameters for low-dose alcohol effects on alcoholic hepatitis." (PMID 32630199, 2020).
ileitis (23 papers, 2011 to 2024). "Our results showed that the induction of ileitis was associated with the presence of both Th1- and Th2-type effector responses, since we observed increased secretion of IFNγ, as well as IL-4 and IL-5." (PMID 23977323, 2013). "It was previously shown that IL-22 can upregulate IL-18 production from intestinal epithelial tissues to enhance immune cell IFNγ production in T. gondii-induced ileitis." (PMID 36361787, 2022). "Damaging control of ileitis by regulating levels of IFNγ, IL-23, and IL-17 and maintaining the fine tuning of MMPs and other enzymes and pro-zymogen enhancers, inducers, and/or converters are fundamental." (PMID 28955329, 2017). "However, contradictory reports indicate that although wild-type and Tlr9−/− mice exhibit a comparable degree of ileitis upon oral Toxoplasma infection, the latter develops a higher parasite burden and higher IFNγ and NO levels." (PMID 33178630, 2020). "Treatment of resveratrol suppresses cyclooxygenase-2 activity and modulates interferon-gamma (IFN-γ), TNF-α, IL-6 and MCP-1 expression in experimental ileitis." (PMID 22069489, 2011).
Infertility (23 papers, 2008 to 2025). "In women with PCOS-related infertility, IFNG levels in peripheral blood and follicles are significantly higher than in normal women, and the incidence of granulosa cell apoptosis in women with PCOS is higher than in the control group." (PMID 40083347, 2025). "In our study, we used the HEC-1A and HEC-1B cell lines treated with TNFα and IFNγ to model possible fertile/infertile pathologies." (PMID 33596915, 2021). "Emerging data shows involvement of Inc stimulated CD4 positive T cells in aiding host immunity in infected fertile and infertile women through the secretion of interferon gamma." (PMID 19698128, 2009). "Overall our data shows that CT IncB and IncC are able to upregulate expression of cytokines, namely interferon-gamma, IL-12, IL-23 and GM-CSF in CT-positive fertile women while expression of IL-1 Beta, IL-4, IL-5, IL-6 and IL-10 were upregulated in CT-positive infertile women." (PMID 19698128, 2009). "E2 level was negatively correlated with interferon gamma (IFN-γ) level and positively correlated with PD-1 level in serum CD4+ and CD8+ T cells of infertile women with PCOS." (PMID 36755917, 2023). "Positive correlation (P < 0.05) was found between Interferon-gamma and T-Bet levels in CT-positive fertile women and IL-4 mRNA and GATA3 levels in CT-positive infertile patients upon IncB and IncC stimulation." (PMID 19698128, 2009). "UC-MSCs also emerged to be beneficial in the revival of infertility in a mouse model of PCOS induced by dehydroepiandrosterone via inactivation of proinflammatory cytokines, for instance, IL- 1β, tumor necrosis factor alpha (TNFα), and interferon gamma (IFN-γ)." (PMID 34203240, 2021). "Significant higher expression (P < 0.05) of Interferon-gamma, IL-12, IL-23 and GM-CSF were found in Inc-stimulated CD4 enriched cervical cells of CT-positive fertile women and contrastingly high IL-1 Beta, IL-4, IL-5, IL-6 and IL-10 levels were found in CT-positive infertile women." (PMID 19698128, 2009).
primary immunodeficiency (23 papers, 2005 to 2026). "Then, we get the pathway such as response to interferon-gamma, Th17 cell differentiation, proteasome, and primary immunodeficiency which is largely associated with TB through KEGG, GO, and GSEA." (PMID 34671419, 2021). "Primary immunodeficiencies that predispose children to NTM infections include defects in cellular immunity and interferon-gamma pathways, such as Mendelian susceptibility to mycobacterial diseases, a rare monogenic defect affecting interferon-gamma function." (PMID 40842793, 2025). "The most significant pathways in Jersey cows were positive regulation of interferon-gamma production, lymphocyte differentiation, side of membrane, natural killer cell-mediated cytotoxicity and primary immunodeficiency." (PMID 30558534, 2018). "Three pathways related to immune infiltration were positively correlated, including primary immunodeficiency, Immunoregulatory interactions between a lymphoid and a non-lymphoid cell, and Interferon gamma signaling." (PMID 36936420, 2023). "GSTK1 expression was positively enriched in immune infiltration pathways, including primary immunodeficiency (PID), immunoregulatory interactions between lymphoid and non-lymphoid cells (IGI), and interferon gamma signaling (IFN-γ)." (PMID 36936420, 2023).
skin cancer (23 papers, 2012 to 2026). "Gene set variation analysis showed that enriched gene signatures in skin tumors included the interferon-gamma response, the interferon-alpha response, and JAK/STAT3 signaling." (PMID 40282557, 2025). "Anti-tumor immune molecules IL-12 as well as interferon-gamma (IFN-γ) play crucial roles in preventing the development of skin cancers." (PMID 33917793, 2021). "Among anti-tumor immune cells and cytokines are IL-12 and interferon-gamma (IFN-γ) that play central roles in limiting skin cancer development." (PMID 31051015, 2016). "IFNγR1 and inducible nitric oxide synthase-2 (NOS2) expression in recipient mice were also required for tumor regression which indicated that CTL-expressed-IFNγ targeted host cells to eliminate skin tumors." (PMID 23060881, 2012). "To better understand mechanism(s) underlying treatment benefits associated with skin immunization, we monitored IFNγ+CD8+ T cell frequencies in the skin tumor-draining lymph nodes (tdLN) of mice receiving skin versus DC-based genetic immunization." (PMID 33408093, 2021). "Notably, IL-12 and IFNγ are well-known drivers of cytotoxic T cells, which inhibit initiation and progression of skin cancer." (PMID 26090614, 2015). "Moreover, in the E.G7-OVA/C57Bl/6 mouse model of intraocular tumor development we observed that CD8+ T cells which infiltrated intraocular tumors expressed IFNγ at levels which were equivalent to those observed in CD8+ T cells that infiltrated skin tumors." (PMID 23060881, 2012). "For example, regression of established E.G7-OVA skin tumors by CD8+ OT-I CTL effectors required IFNγ but not perforin expression by transferred T cells." (PMID 23060881, 2012). "Due to the lack of standard immunocompetent mousemodels of MCC, to investigate the impact of adding IFNγ to reprogrammingNPs in vivo, we used the B16F10 mouse model of subcutaneousmelanoma to investigate our hypothesis in the most common, systemicallyaggressive skin cancer type." (PMID 37797944, 2023).
systemic inflammatory response syndrome (23 papers, 2011 to 2025). SIRS is a serious condition related to systemic inflammation, organ dysfunction, and organ failure. "In addition, a study on systemic inflammatory response syndrome demonstrated RKIPs ability to regulate type I/II interferon production as RKIP deficient cells generate a significantly diminished interferon gamma (IFNγ) response by CD8 + T cells compared to wild type." (PMID 41327312, 2025). "This immune-mediated injury, accompanied by elevated concentrations of IL-1, IL-2, IL-10, and IFNγ, would lead to systemic inflammatory response syndrome (SIRS)." (PMID 35464491, 2022). "Accordingly, an in silico analysis of published IFNγ and IL10 values in bacteremic and non-bacteremic patients with the Systemic Inflammatory Response Syndrome supported this association between the ratio and pathogen burden." (PMID 33767693, 2021).
coccidioidomycosis (22 papers, 2005 to 2025). A fungal infection caused by Coccidioides immitis. "Immune responses against histoplasmosis, coccidioidomycosis, talaromycosis, and blastomycosis are governed by the coordinated interactions between fungicidal macrophages and T cells producing IFNγ." (PMID 38143753, 2023). "Recently there has been growing interest in the development of interferon gamma (IFN-γ) release assays in diagnosing and evaluating immune responses in patients with coccidioidomycosis." (PMID 37233224, 2023). "A combination of IFNγ and dupilumab, i.e., IL-4/IL-3 receptor inhibitor, can promote remission in refractory disseminated coccidioidomycosis where inborn errors of immunity were detected in the child." (PMID 38143753, 2023). "Lower PCT is consistent with the cell-mediated immune response against Coccidioides infection because the production of interferon gamma from type-1 T-helper cells impedes PCT upregulation." (PMID 35608552, 2022). "Lastly, our sample size was relatively small and might have contributed to not detecting differences that actually exist between dogs with pulmonary and disseminated coccidioidomycosis, in particular the pattern of IFNγ production between the two groups." (PMID 36836327, 2023). "In patients with pulmonary coccidioidomycosis, several cytokines were increased in high concentrations, including granulocyte-macrophage colony-stimulating factor (GM-CSF), interleukin-1β (IL-1β), interferon gamma (IFN-γ), IL-2, IL-13, and tumor necrosis factor alpha (TNF-α)." (PMID 37233224, 2023). "Recombinant interferon-gamma (IFNγ) has been used to aid pathogen clearance in IEIs mycobacterial disease, CGD and Coccidioidomycosis." (PMID 36891233, 2023). "Furthermore, studies have shown increases in cytokines such as interferon gamma (IFNγ), tumor necrosis factor alpha (TNFα), and interleukin (IL)-17 in mononuclear cells from bronchoalveolar lavage fluid (BALF) from patients with pulmonary coccidioidomycosis." (PMID 31572393, 2019).